HOXC10 (homeobox C10)
Diseases named in the same sentence as HOXC10 in open-access papers (continued):
Sharing a sentence is not in itself a finding about the gene and the disease.
colon cancer (1 paper, 2023). "For example, the upregulated HOXC10 promotes ESCC proliferation both in vitro and in vivo, HOXD13 has been reported to promote the malignant progression of colon cancer." (PMID 37393256, 2023).
esophageal cancer (1 paper, 2023). A primary or metastatic malignant neoplasm involving the esophagus. "Based on the bioinformatics analysis, FOXA3 is a similar gene to HOXC10, and their expression is positively correlated in esophageal cancer." (PMID 37876483, 2023). "Based on the STRING and GEIPA databases, FOXA3 and HOXC10 were co-expressed and their expression was positively correlated in esophageal cancer (R = 0.46, p = 9.1e-11)." (PMID 37876483, 2023). "FOXA3 was predicted to be a similar gene to HOXC10 in esophageal cancer." (PMID 37876483, 2023).
gastric adenocarcinoma (1 paper, 2023). "A previous bioinformatics analysis revealed that HOXC genes (HOXC8, HOXC9, HOXC10, HOXC11, HOXC12, and HOXC13) might participate in pathogenesis of gastric adenocarcinoma." (PMID 37724126, 2023).
Hernia (1 paper, 2020). "In this study, HOXC10 was downregulated in animals affected with scrotal hernia and, although it has not yet been associated with hernias, the HOXA10 gene, which belongs to the same gene family, has already been considered a candidate for causing this pathology." (PMID 31973088, 2020).
Hypertension (1 paper, 2023). The presence of chronic increased pressure in the systemic arterial system. "Multiple HOXC genes: HOXC-AS1-3, HOXC4, HOXC5, HOCX6, HOXC8, HOXC9 and HOXC10 were also shared between subsets of GORD, hypertension and precordial pain." (PMID 37410157, 2023).
metastasis (1 paper, 2022). The spread or migration of cancer cells from one part of the body (where they first appeared) to another. "The elevated HOXC10 expression was positively correlated with tumor differentiation, tumor invasion, lymph node metastasis, distant metastasis, and higher American Joint Committee on Cancer (AJCC) stage." (PMID 36186898, 2022).
ovarian tumour (1 paper, 2020). "In summary, upregulation of HOXC10 expression increased ovarian tumour metastasis, and this effect was abrogated by miR-222-3p in vivo." (PMID 32897245, 2020).
skin aging (1 paper, 2025). The gradual irreversible changes in structure of skin that occur as a result of the passage of time.. "In this study, we explored the protective function of HOXC10 against skin aging and demonstrated that HOXC10 activates the canonical Wnt/β-catenin signaling pathway by suppressing frizzled 6 (FZD6) transcription, thereby delaying the cell senescence and skin aging processes." (PMID 41268215, 2025).
tumor (33 papers, 2015 to 2026). "Recent research has demonstrated that HOXC10 expression is significantly associated with tumor metastasis and invasion in different tumors." (PMID 39191757, 2024). "Results showed that high expression of HOXC10 in the tumor tissue was found associated with poor prognosis." (PMID 37733108, 2023). "Some signal pathways associated with tumor were totally positively enriched in HOXC10 for whole cancers." (PMID 38154103, 2023). "HOXC10 overexpression was linked to lymph node metastases, distant metastasis, worse tumor differentiation, and higher TNM stage." (PMID 36186898, 2022). "Recent studies revealed that HOXC10 expression was strongly linked to tumor metastasis and invasion in various tumors." (PMID 34113572, 2021). "In both cohorts, elevated HOXC10 expression was positively correlated with maximal tumor size, tumor encapsulation loss, and higher tumor-nodule-metastasis (TNM) stage." (PMID 32206125, 2020). "Overexpression of HOXC10 positively correlated with maximal tumor size, tumor encapsulation loss and high TNM stage and was an independent risk factor for higher recurrence and shorter overall survival in HCC patients." (PMID 32206125, 2020). "HOXC10 was associated with tumor mutation burden and microsatellite instability." (PMID 38154103, 2023). "HOXC10 also was associated with tumor microenvironment and immune status." (PMID 38154103, 2023). "In a separate study of HCC, induction of HoxC10 downstream of interleukin-1β (IL-1 β) resulted in reduced tumour encapsulation leading to increased tumour-nodule-metastasis (TNM) stage and poor prognosis." (PMID 41535654, 2026). "Previous research has shown that HOXC10 is overexpressed in numerous tumors, where it promotes tumor cell proliferation through the activation of signaling pathways such as the MAPK and ERBB3/PI3K/AKT axes." (PMID 41268215, 2025). "Substantial literature has shown that HOXC10 acts as a tumor-promoter in the occurrence and development of many solid tumors." (PMID 37876483, 2023). "Then, we evaluated the effect of HOXC10 on tumor microenvironment and immune infiltration in cancers." (PMID 38154103, 2023). "Univariate analysis revealed that HOXC10 expression (P = 0.007), Tumor size (P = 0.024), Grade stage (P = 0.032), TNM stage (P = 0.017) and T stage (P = 0.017) were significant prognostic factors for OS." (PMID 37733108, 2023). "Abnormal expression HOXC10 involved in multiple signaling pathways, molecular features, and tumor microenvironment." (PMID 38154103, 2023). "High HOXC10 level was correlated with higher tumor invasion depth (P = 0.006) and the later TNM stage (P = 0.006)." (PMID 37876483, 2023). "We estimated the correlations of HOXC10 with tumor microenvironment using ESTIMATE and stromal scores." (PMID 38154103, 2023). "New evidence suggests that HOXC10 acts as an oncogene and can promote tumor proliferation 11, invasion 12 and metastasis." (PMID 36186898, 2022). "In previous study, it was shown that the expression of HOXC10 was significantly higher in tumor tissues compared with the normal tissues." (PMID 36186898, 2022). "The immunohistochemistry pictures revealed that CRC tissues had considerably greater HOXC10 expression than non-tumor tissues." (PMID 36186898, 2022). "The HOXC10 mRNA levels in CRC tissues were greater than in non-tumor tissues and normal colorectal epithelial specimens." (PMID 36186898, 2022). "The positive correlation between the expression of HMS and HOXC10 was conserved not only in established cancer cell lines but also in human tumor tissues making a strong case that HMS sustains HOXC10 levels during oncogenic transformation." (PMID 34302808, 2021). "High HOXC10 expression is significantly to enhance tumor proliferation, invasiveness, recrudesce and drug resistance." (PMID 34113572, 2021). "Further research revealed that the molecular mechanisms by which HOXC10 regulates tumor metastasis and invasion." (PMID 34113572, 2021).
tumor (continued). "In this section, we systematically summarize the functions and potential molecular mechanisms of HOXC10 in tumor occurrence, metastasis and drug resistance." (PMID 34113572, 2021). "HOXC10 expression is increased in tumor tissue and promotes cell proliferation, migration, and invasion, as well as colony formation, an aggressive cell phenotype, and inducement of immunosuppressor gene expression." (PMID 33498521, 2021). "Among the HOX genes, HOXC family members exhibit markedly increased expression in many tumours, and several studies have focused on the HOXC10 gene." (PMID 32897245, 2020). "Overexpression of HOXC10 in A549 cells conveyed increased proliferation, reduced apoptosis, and accelerated tumor growth when transplanted into nude mice." (PMID 32687064, 2020). "Increased HOXC10 expression was significantly associated with the FIGO stage (P=0.0271), the tumour distant metastasis (P=0.0220) and the survival status at the time of analysis (P=0.0249)." (PMID 32897245, 2020). "In vivo, a decrease in hepatic metastasis was seen in xenograft mice harbouring tumours with stable HOXC10 overexpression after miR-222-3p agomir (an overexpression reagent) injection." (PMID 32897245, 2020). "More importantly, HOXC10 overexpression in A549 cells was sufficient to promote tumor growth in vivo." (PMID 32687064, 2020). "Several investigations into tumor progression have indicated the pro-metastasis role of HOXC10 20,22." (PMID 31528218, 2019). "Suppression of HOXC10 significantly inhibited tumor growth, and reduced tumor volume (P < 0.001) and tumor weight (P < 0.001)." (PMID 31528218, 2019). "Similarly, HOXC10, a transcription factor, promotes tumor progression by inducing cell proliferation and inhibiting apoptosis." (PMID 40260244, 2025). "More importantly, we found that combining HOXC10 inhibition and STAT3i could confer a marked survival benefit in this aggressive, refractory tumor in an intracardiac injection mouse model." (PMID 39191757, 2024). "HomeoboxC10 (HOXC10), a highly conserved transcription factor, is crucially involved in embryonic morphogenesis during development, and exploits DNA replication and embryonic capacity for tumor development." (PMID 37876483, 2023). "This indicates that HOXC10 regulates ESCC tumor cell proliferation in vivo." (PMID 37876483, 2023). "In addition, HOXC10 has been shown involved in tumor proliferation, migration, and invasion in numerous studies." (PMID 37733108, 2023). "Furthermore, tumor-bearing mouse models studies demonstrated that HOXC10 through knockdown techniques significantly suppressed ESCC tumor growth." (PMID 37876483, 2023). "The correlations of HOSC10 with immune score and immune-related genes showed that HOXC10 may promote or inhibit tumor occurrence and progression via regulating immune response." (PMID 38154103, 2023). "We first evaluated the expression levels of HOXC10 between normal and tumor pan-cancer tissues." (PMID 38154103, 2023). "Additionally, it was observed from IHC results that the expression level of Ki67 in HCC tumor tissues of the xenografted mice was markedly increased in HOXC10 overexpression mice compared with the control group." (PMID 37733108, 2023). "In the HepG2 xenograft models, HOXC10 increased the tumor volume and weight compared with control." (PMID 37733108, 2023). "HOXC10 overexpression accelerated tumor growth in mice compared with the control group in mice." (PMID 37733108, 2023). "The impact of HOXC10 on ESCC tumor growth in vivo was examined in tumor-bearing mouse models." (PMID 37876483, 2023). "Besides, we observe lower methylation levels of HOXC10 than HOXD1 on both tumor and normal samples in TCGA dataset, which is also revealed by the sequencing results that fewer methylation events occur on both tumor and normal samples for HOXC10 than HOXD1." (PMID 36447287, 2022).
tumor (continued). "HOXC10 was reported upregulated in ESCC, and its high expression contributed to the proliferation and migration of tumor cells, indicating that HOXC10 could be an unfavorable prognostic predictor." (PMID 36447287, 2022). "HOXC10 upregulation can promote tumor proliferation 11, invasion 12, and metastasis." (PMID 36186898, 2022). "Recent evidences revealed that HOXC10 regulated EMT to induce tumor invasion and metastasis." (PMID 34113572, 2021). "Dysregulation of HOXC10 expression is common in tumors and indicates that HOXC10 may contribute to tumor occurrence and development." (PMID 34113572, 2021). "We also found that HOXC10 silencing notably enhanced cell apoptosis of tumor tissues in mice." (PMID 35201457, 2021). "Moreover, IHC staining results showed that HOXC10 knockdown caused a down-regulation of HOXC10, Slug, YAP1 and TAZ in the tumor tissues of mice." (PMID 35201457, 2021). "Several studies have revealed the HOXC10 molecular mechanisms that regulate tumor development." (PMID 34113572, 2021). "Moreover, HOXC10 upregulation significantly increases tumour volumes and promotes the migration and invasion of gastric cancer cells." (PMID 32897245, 2020). "In summary, we report HOXC10 as a novel tumor promoting oncogene in NSCLC cells." (PMID 32687064, 2020). "Taken together, our findings indicate that HOXC10 may promote tumor progression by enhancing cell proliferation and metastasis in OSCC." (PMID 31528218, 2019). "Western blotting results from tumor xenograft samples showed PTEN expression level was decreased and p-AKT and mTOR expression was significantly increased in tumors induced by HOXC10 overexpression." (PMID 37733108, 2023). "The results of ANKRD52 level expressed that the HOXC10, KNOP1, and TRIM45 in the tumor tissue were higher in the paracancerous tissue, and the opposite was true for SGPP1." (PMID 37521466, 2023). "Among them, HOXC11, HOXC10, HOXC8, and HOXC12 interact with HOTAIR in gastrointestinal tumors to jointly promote tumor formation and development." (PMID 36924407, 2023). "In summary, we discovered that overexpression of HOXC10 contributed to CRC metastasis by upregulating CXCL5 expression and increased the infiltration of MDSCs into the tumor microenvironment." (PMID 36186898, 2022). "HOXC10 overexpression is also closely related to TNM stage, cell proliferation, metastasis, and tumor growth in these tumors." (PMID 34113572, 2021). "We analyzed tumor samples of the TCGA-LUAD database and observed a positive correlation between the expression of HMS and HOXC10." (PMID 34302808, 2021). "In this study, we assessed the expression of HOXC10 in human NSCLC cell lines and analyzed the functions of HOXC10 in tumor progression in vitro and in vivo." (PMID 32687064, 2020). "In this study, bioinformatics analysis showed that HOXC10 was the most highly expressed HOX genes in LUAD with metastasis than that without metastasis and HOXC10 levels were significantly higher in LUAD versus those in non-tumor tissues." (PMID 38154103, 2023). "Furthermore, to analyze the effect of tumor stage and grade in LUAD patients with overexpressed HOXC10 on poor DMFS, LUAD patients were first stratified into different groups of Stage I to IV and Grade I to III." (PMID 38154103, 2023). "HOXC10 knockout significantly inhibited ERK phosphorylation and the tumor cell proliferation." (PMID 34113572, 2021). "In summary, our study shows that HOXC10 is overexpressed in OSCC cells and tumor tissues." (PMID 31528218, 2019). "However, HOXC10 influenced tumour metastasis but not cell proliferation in OC, as demonstrated both in vitro and in vivo." (PMID 32897245, 2020).
cancer (28 papers, 2019 to 2026). A tumor composed of atypical neoplastic, often pleomorphic cells that invade other tissues. "We next clarified the underlying mechanism by which HOXC10 downregulation suppressed KRAS-mutant cancer growth and bone metastasis by utilizing genome-wide RNA-seq analysis." (PMID 39191757, 2024). "HOXC10 expression is dysregulated in various cancers, acting as a carcinogenic driver associated with poor prognosis." (PMID 37521466, 2023). "To explore the immune regulation role of HOXC10 in cancers, we analyzed the associations between HOXC10 expression and immune score and immune-related genes." (PMID 38154103, 2023). "In these DEGs, several cancer‐associated genes such as HOXC10, THBS1, CDKN2B, PAX2 and H19 were significantly associated with AML biology." (PMID 31794134, 2020). "Among these, HOXB7, HOXA13, HOXA10, and HOXC10 have been associated with cancer." (PMID 38761291, 2024). "Anomalous HOXC10 expression is strongly associated with cancer occurrence and progression." (PMID 34113572, 2021). "Thus, we report a novel lncRNA, HMS, functions as a HOXC10mRNA stabilizing factor by associating with the HuR to stabilize HOXC10 mRNA, which has an essential role in the proliferation of cancer cells." (PMID 34302808, 2021). "Reports suggest that anomalous HOXC10 expression is strongly associated with the occurrence and progression of cancers and HOXC10 may be a potential prognostic factor and therapeutic target." (PMID 34113572, 2021). "Thus, we searched for a link between HOXC10 expression and cytosine methylation in the HOXC10 promoter associated CpG island from the the Cancer Cell Line Encyclopedia (CCLE) data set." (PMID 32687064, 2020). "Tartrate-resistant acid phosphatase (TRAP) staining revealed that the number and size of TRAP+ osteoclasts induced by the conditioned medium from STAT3 inhibition, together with HOXC10-inhibited cancer cells, were significantly deceased." (PMID 39191757, 2024). "HOXC10 was mainly expressed in the nucleus of cancer cells, and HOXC10 expression was dramatically higher in LUAD tissues than in benign lung lesions." (PMID 38154103, 2023). "To explore the biological function roles of HOXC10 in cancers, we analyzed the correlations of the pathway’s enrichment differences with HOXC10 expression." (PMID 38154103, 2023). "HOXC10 has been reported to activate the MAPK pathway to regulate cancer proliferation and metastasis." (PMID 37876483, 2023). "In this study, we first analyzed the differential expressions of HOXC10 in pan-cancer and corresponding normal samples, and explored its prognosis roles in cancers." (PMID 38154103, 2023). "One hand, the correlation of HOXC10 with immunes in cancers need to be verified in vivo and in vitro." (PMID 38154103, 2023). "Our results indicated that HOXC10 was abnormal expression in most cancers, which emphasized the important roles of HOXC10 in cancers." (PMID 38154103, 2023). "Many studies have shown that abnormal expression of HOXC10 contributes to the malignant progression of several types of cancers." (PMID 38154103, 2023). "In summation, in this study we demonstrate that HMS recruits the RNA stabilizing protein called HuR to the 3′ untranslated region of oncogene HOXC10, thereby stabilizing its levels and maintaining the oncogenic properties of the cancer cells." (PMID 34302808, 2021). "Second, the high levels of both HMS and HOXC10 observed in cancer patient samples are associated with low survival probability, which further emphasizes that HMS and HOXC10 both contribute to human oncogenic pathology." (PMID 34302808, 2021). "In this review, we summarize HOXC10 gene structure and expression as well as the role of HOXC10 in different human cancer processes." (PMID 34113572, 2021). "This review will provide insight into the status of HOXC10 research and help identify novel targets for cancer therapy." (PMID 34113572, 2021).